OLA1P2 (OLA1 pseudogene 2)
Gene: Processed pseudogene on chromosome 17 (20,775,642 to 20,776,905, forward strand). Ensembl gene ENSG00000213671.
Diseases named in the same sentence as OLA1P2 in open-access papers:
OLA1P2 is named in the same sentence as 10 diseases in open-access papers, as found by Europe PMC text mining. Sharing a sentence is not in itself a finding about the gene and the disease. The quoted sentences say what the papers report.
colorectal cancer (3 papers, 2016 to 2024). A primary or metastatic malignant neoplasm that affects the colon or rectum. "In a similar study on colorectal cancer, after treating the cells with aspirin (100 μM), 28 lncRNAs increased that the most considerable change among them belonged to lncRNA OLA1P2." (PMID 34926688, 2021). "We identify an aspirin-induced upregulated lncRNA, OLA1P2, in human colorectal cancer." (PMID 26898989, 2016). "OLA1P2 could block phosphorylated STAT3 homodimer formation and activate the STAT3 signaling pathway, inhibiting colorectal cancer cell growth and metastasis." (PMID 34926688, 2021).
colon cancer (1 paper, 2016). "OLA1P2 expression was dramatically induced after aspirin treatment in oral cancer, gastric cancer, and colon cancer cell lines, but not in esophageal cancer, liver cancer, and pancreatic cancer cell lines." (PMID 26898989, 2016).
gastric cancer (1 paper, 2016). A primary or metastatic malignant neoplasm involving the stomach. "In addition to CRC, OLA1P2 was also markedly induced by aspirin in oral cancers and gastric cancers." (PMID 26898989, 2016). "We identified an aspirin-induced upregulated lncRNA, OLA1P2, in human CRC, oral cancer, and gastric cancer cells." (PMID 26898989, 2016).
cancer (1 paper, 2016). A tumor composed of atypical neoplastic, often pleomorphic cells that invade other tissues. "In this study, we investigated the lncRNA expression profiles associated with aspirin treatment and showed that lncRNA OLA1P2 could be dramatically induced by aspirin in cancer cells." (PMID 26898989, 2016). "Additionally, low OLA1P2 levels are associated with malignant transformation and lower overall survival in cancers." (PMID 26898989, 2016). "To identify the targets regulated by OLA1P2, we performed a global gene expression profiling analysis in OLA1P2-silenced primary cultured cancer cells obtained from eight clinical CRC tissues." (PMID 26898989, 2016). "Increased levels of OLA1P2 in clinical cancer tissues obtained from patients with regular use of aspirin were determined by qRT-PCR analysis." (PMID 26898989, 2016). "Regular use of aspirin dramatically decreases the number of metastatic nodules of cancer cells in immunodeficient mouse lungs, and OLA1P2 silencing markedly weakens the anti-metastatic activity of aspirin in the lungs." (PMID 26898989, 2016). "We further observed the anti-proliferative activity of OLA1P2 in cancer cell lines; OLA1P2 largely mediated the anti-invasive activity of aspirin in different cancer cell lines." (PMID 26898989, 2016). "Using qRT-PCR analysis, we confirmed these upregulated STAT3 targets in OLA1P2-silenced cancer cell lines." (PMID 26898989, 2016). "To determine whether STAT3 expression was regulated by OLA1P2, we infected cancer cells with a lentivirus expression vector (lenti-OLA1P2) or a short hairpin RNA vector (shRNA-OLA1P2)." (PMID 26898989, 2016). "Considering that many digestive system cancers could possess similar characteristics, we assessed OLA1P2 expression in other types of cancer cells." (PMID 26898989, 2016). "More than 2 years after surgery, OLA1P2 overexpression may suppress cancer cell proliferation and metastasis, thus resulting in a lower rate of cancer recurrence." (PMID 26898989, 2016). "Given that inhibition of STAT3 homodimers formation diminished STAT3 activity, STAT3 may represent a potential therapeutic target for OLA1P2 in cancer chemotherapy." (PMID 26898989, 2016). "Our findings suggested that aspirin could suppress cancer cell growth and metastasis through the induction of lncRNA OLA1P2 transcription and the subsequent blocking of phosphorylated STAT3 (signal transducer and activator of transcription 3) homodimers formation." (PMID 26898989, 2016). "RNA FISH technology combined with immunofluorescence analysis confirmed the co-localization of lncRNA OLA1P2 and phosphorylated STAT3 (Tyr705) protein in the cancer cells." (PMID 26898989, 2016). "Aspirin dramatically increased FOXD3 concentrations in the nuclei of cancer cells and effectively promoted FOXD3 interaction with OLA1P2 promoter regions, providing convincing evidence that FOXD3 is a new aspirin target that could function in the control of lncRNA transcription." (PMID 26898989, 2016).
tumor (1 paper, 2016). "Lower levels of OLA1P2 correlated with more advanced pathology grade, suggesting an association between OLA1P2 expression and tumor progression." (PMID 26898989, 2016).
OLA1P2 also shares sentences with these, for which no sentence is quoted: digestive system cancer (1 paper); esophageal cancer (1); liver cancer (1); oral cancers (1); pancreatic cancer (1).